HIF1A (hypoxia inducible factor 1 subunit alpha)
Diseases named in the same sentence as HIF1A in open-access papers (continued):
Sharing a sentence is not in itself a finding about the gene and the disease.
tumor (continued). "Even when drugs are taken up into tumor cells, the expression of HIF-1α promotes drug efflux via activation of the drug efflux pump, membrane-resident P-glycoprotein." (PMID 35631488, 2022). "Another study showed that SIRT3 represses tumor growth by downregulating HIF-1α and reducing ROS accumulation." (PMID 36211825, 2022). "Alkaloids: In HCT116 and SW620 cells, matrine inhibited the expression levels of downstream targets of glucose metabolism GLUT1, HK2 and LDHA by down-regulating HIF-1α mRNA and protein expression, consequently impacting tumor cell survival." (PMID 36339566, 2022). "High expression levels of HIF-1α and its target genes have been described to promote tumor aggressiveness, chemoresistance, and poor overall patient survival in PDAC22–27." (PMID 35440539, 2022). "In accordance with the previous studies in vitro, we verified that HIF1α knockdown suppressed CAF-induced lung metastasis in NOD/SCID subcutaneous tumor model, which was also observed in H&E staining." (PMID 35589690, 2022). "pH-sensitive nanosystems can exploit hypoxic tumor microenvironments, thereby reducing the expression of pro-angiogenic factors via downregulating the expression of HIF-1α." (PMID 36153528, 2022). "HIF-1α is reported to increase sEV secretion by B cells of tumor mice in a manner dependent on Rab27a." (PMID 36531060, 2022). "The reduction in tumor-specific expression of HIF-1α across the cisplatin, bevacizumab + metformin, bevacizumab + cisplatin, and metformin + cisplatin groups were not statistically significant compared with the control." (PMID 36046821, 2022). "Solid tumor cells commonly encounter low nutrient and oxygen conditions in their region of origin during tumor development and progression, and hypoxic conditions in solid tumors are known to promote the activation of HIF-1α." (PMID 36064348, 2022). "HIF-1α is an important hypoxic stress factor induced by tumor hypoxic microenvironment and is closely related to several aspects of tumor formation." (PMID 36385964, 2022). "It has been shown that Sept9 can bind and stabilize Hif-1α, promote its transcriptional expression, and promote angiogenesis and tumor growth." (PMID 35096204, 2022). "We then discuss our recently published data on how targeting hypoxia, by deleting a critical domain in HIF-1α, contributes to the improvement of the anti-tumor immune response." (PMID 35795658, 2022). "The overexpression of β-arrestin 2 in GBM slows HIF-1α signaling, preventing tumor growth and angiogenesis." (PMID 36010884, 2022). "Tumor cells at the outer part of the “pseudo-papillary” structure were CA9-positive (CA9+)/HIF-1α+, whereas cells at the inner part of this structure were CA9−/HIF-1α+ and nestin+/FOXM1+." (PMID 35785200, 2022). "More importantly, the results provide evidence that HIF-1α is involved in coordinating PD-L1 expression on tumor-infiltrating myeloid cells in the TME." (PMID 35239514, 2022). "Conversely, tumor cell survival can be suppressed by hypoxia-induced factor 1α (HIF1α), a subunit of HIF-1 and a heterodimeric transcription factor, showing close association with the local suppression of anti-tumor immune responses." (PMID 35287356, 2022). "Specifically, HIF-1α functions as a regulator of hypoxia-induced transcription to promote tumor glycolysis, angiogenesis, invasion and metastasis." (PMID 35764883, 2022). "Upon hypoxic tumour microenvironment and subsequent HIF-1α stabilisation, the urokinase-type plasminogen activator receptor (uPAR) was found stimulated as well." (PMID 36224457, 2022). "HIF-1α protein expression was significantly increased in both cell lines at 2% O2, a pO2 which resembled the hypoxic tumor microenvironment." (PMID 36230699, 2022). "For example, Lnc P21 can form a positive-feedback loop with HIF-1α, promoting hypoxia-related glycolysis in tumor cells." (PMID 36380019, 2022). "The downregulation of miR-1 significantly increased HIF-1α expression, resulting in enhanced tumor glycolysis." (PMID 36005571, 2022).
tumor (continued). "Although studies have demonstrated that IDH2/HIF1α pathway was indispensable in tumor growth, the mechanism under IDH2-HIF1α regulation kept mysterious." (PMID 36304962, 2022). "A meta-analysis was performed to assess the correlation between HIF-1α expression level and tumor clinicopathological characteristics." (PMID 35845307, 2022). "The AMPK‐dependent signaling triggered by SCT‐1015 downregulated HIF1α protein abundance to suppress the tumor progression in HCC cells and the xenograft mice model." (PMID 35298869, 2022). "The optimal antitumor effects observed using nano-Pt/VP@MLipo were also explained with in situ reversion of hypoxia, as documented by reduced pimonidazole staining and HIF-1α expression in tumor tissues, which would potentially enhance VP-mediated PDT." (PMID 36139623, 2022). "The overexpression of WNT, HIF-1α, and EGRF in colorectal cancer was previously linked to the promotion of angiogenesis and proliferation of tumor cells." (PMID 36012159, 2022). "Studies have shown that HDACi can inhibit tumor angiogenesis by inhibiting the expression of HIF-1α." (PMID 36139386, 2022). "PDAC tumor biology relies on hypoxia and HIF1α signaling to control tumor-promoting stromal programs, which facilitate progression and tumor cell invasiveness." (PMID 35954462, 2022). "In summary, this study showed that chrysin inhibits tumor growth and VM by inhibiting HIF-1α, SPHK-1, and phospho-AKT/GSK-3β signaling in PC-3 cells under hypoxia." (PMID 36139362, 2022). "PPARα activation supports the binding of HIF-1α to the von Hippel–Lindau tumor suppressor, thereby inducing HIF-1α degradation through the ubiquitin–proteasome pathway." (PMID 35954274, 2022). "In the following, we summarize the lncRNAs that are directly regulated by HIF-1α to promote tumor EMT and their mechanisms of action to broaden the understanding of clinical tumor therapy targeting lncRNAs (Table A1)." (PMID 36139386, 2022). "Foxp3-positive cells mainly assemble in hypoxic tumor regions, where cells also express high levels of HIF-1α and TGF-β." (PMID 35625561, 2022). "Immunostaining assays by several groups have shown that HIF-1α is present in 70–77% of CRC tumor cells, perinecrotic tissue, and blood vessels." (PMID 35741024, 2022). "In conclusion, our results established HIF-1α as a master regulator of lipid metabolism in fibroblasts, elevating the abundance of LDs and leading to a tumor-promotion phenotype of lung fibroblasts." (PMID 36439884, 2022). "IDH3α downregulation induces HIF-1α stabilization and glycolysis in CAFs and promotes melanoma and colorectal cancer tumor growth." (PMID 35814364, 2022). "Knockout of Glut‐1 or HIF‐1α led to significantly more apoptotic cells in tumour tissues compared with the control, similar to the effects of 12 Gy X‐ray irradiation." (PMID 35415942, 2022). "As expected, our IHC staining analysis indicated hypoxia-inducible factor 1 alpha (HIF1α) displayed a tendency of upregulated-expression in tumor tissues compared with adjacent normal tissues." (PMID 35484132, 2022). "The role of HIF1α in regulating several signaling pathways that result in tumor cell migration has been extensively described in previous reports, and it is widely accepted." (PMID 35054927, 2022). "After 24 h, the mice were sacrificed to evaluate the expression levels of the TLR4/NF-κB/HIF-1α in tumor tissues." (PMID 35464826, 2022). "While our understanding of the hypoxic response has grown tremendously in the 10 years since “HIF1α and HIF2α: Sibling rivalry in hypoxic tumour growth and progression” was published, the role of HIF-α in tumor progression remains controversial." (PMID 35267567, 2022). "In HCC-bearing mice, Par also exhibited an excellent anti-tumor effect, decreasing the tissue levels of P50 and HIF-1α." (PMID 36260873, 2022). "IL-1β activates both RAS and Wnt-1 which mediate the elevation of HIF-1α, thus inducing a HIF-1α/IL-1β autocrine loop in GBM tumor cells." (PMID 35572545, 2022).
tumor (continued). "Under hypoxia, HIF-1α induced by tumor cells can bind to HRE on lncRNA and promote the expression of HIF-1α antisense lncRNA (HIFAL)." (PMID 36139386, 2022). "This coincides with a previous study in tumor cells which showed that the effect of lactate on HIF-1α expression was abolished upon siRNA-mediated knockdown of PHD239." (PMID 36064857, 2022). "Then, HIF-1α transactivates hundreds of genes that enhance aerobic glycolysis and the progression of tumor cells." (PMID 36369467, 2022). "The overexpression of lncRNALET was shown to promote the ubiquitination and degradation of NF90 (double-stranded RNA binding protein) protein and indirectly inhibit the level of HIF-1α protein, thus inhibiting tumor metastasis and glycolysis." (PMID 36124026, 2022). "In a similar study, isoflurane-induced upregulation of HIF-1α, consequently increasing tumor malignancy with increased proliferation and migration, as well as the development of chemoresistance in prostate cancer cells." (PMID 35296017, 2022). "Owing to the essential role of HIF-1α in tumor angiogenesis, we further detected the expression of HIF-1α." (PMID 35291563, 2022). "Compared with free curcumin, the nano-formulation group has increased solubility and anti-tumor activity, which can effectively improve the tumor hypoxic microenvironment and block the occurrence and development of tumors by suppressing HIF-1α." (PMID 36532768, 2022). "The lncRNA linc-RoR, whose expression was increased in hypoxic regions within tumor cell xenografts in vivo, regulated the hypoxic response through a miR-145/HIF-1α signaling module." (PMID 36127332, 2022). "Numerous studies have shown that HIF-1α overexpression is highly related to tumor migration and invasion." (PMID 35860704, 2022). "As an antisense transcript of HIF-1α, Hypoxia-inducible factor 1 alpha-antisense RNA 2 (HIF1A-AS2) has been implicated in the hypoxia-associated tumor processes." (PMID 35212609, 2022). "Glycolysis is not only a key player in providing an energy substrate, it involves the activation of oncogenes such as phosphatidylinositol 3-kinase (PI3K) but also the modulation of HIF-1A and modifies the tumor microenvironment (TME)." (PMID 36553058, 2022). "Within the tumor microenvironment, LA has been shown to induce a protumor M2-like phenotype in stromal macrophages, inducing Hif1α-driven VEGF expression and angiogenesis." (PMID 35362044, 2022). "The results showed that PC saponins can regulate the energy metabolism of tumor cells through the HIF-1α pathway to achieve the effect of inhibiting tumor growth." (PMID 35814470, 2022). "Next, to see the effects of extracellular citrate on HIF1α expression and tumor glycolysis, HCC cell lines were treated with citrate for 24 h under hypoxic conditions." (PMID 35884416, 2022). "We further examined the expressions of CD147 and HIF-1α in 27 tumor specimens of CRC patients treated with preoperative fluorouracil analog–based chemotherapy." (PMID 35898887, 2022). "Mechanistically, SCG2 inhibits tumor growth and angiogenesis by disrupting the activities of HIF-1α/VEGF in malignant CRC tissues." (PMID 35836930, 2022). "BRCA1 was also found to bind and stabilize hypoxia-inducible factor-1α (HIF-1α) and promote tumor survival." (PMID 35453307, 2022). "Many recent studies have demonstrated a strong correlation between elevated levels of HIF-1α and tumor metastasis, angiogenesis, poor patient prognosis, and tumor resistance to therapy." (PMID 35740392, 2022). "The Ref-1/HIF-1α/STAT3/NF-κB signaling node likely contributes to disease attributes linked to TSC pathology, such as inflammation, cell migration/invasion, tumor growth, metabolic transformation, and angiogenesis." (PMID 36551683, 2022).
tumor (continued). "There is also a consensus that hypoxia promotes chemoresistance in several tumor types including BC, mainly through HIF1α-mediated transcriptional regulation of many genes that control drug resistance." (PMID 35205770, 2022). "PGE2 has been demonstrated to induce HIF-1α activation in a relatively less hypoxic microenvironment during the early stages of the tumor." (PMID 36233088, 2022). "In prostate cancer, exercise induced the upregulation of HIF-1α and VEGF via activating MEK/MAPK and PI3K/mTOR signaling pathway, which is associated with a shift to tumor vascular normalization and inhibition of tumor metastasis." (PMID 36313283, 2022). "In most ccRCC tumors, CA IX is frequently expressed at high levels due to the functional inactivation of the VHL tumor suppressor gene that generates defective pVHL protein unable to negatively regulate HIF-1α." (PMID 35109923, 2022). "Accumulation evidence suggests that HIF-1α is the most critical regulator of cancer cell invasion, chemoresistance, and VM formation in tumor microenvironment as it affects various cellular processes, such as epithelial-mesenchymal transition (EMT)." (PMID 34969360, 2022). "The forced expression of miR-199a-5p suppressed COX2 and HIF1-α expression and impaired arsenic-induced angiogenesis and tumor growth." (PMID 36139662, 2022). "As a key regulator of the cell response to hypoxia in the tumor microenvironment, HIF-1α is known to contribute to the maintenance of CSC stemness." (PMID 35935823, 2022). "The hypoxia-inducible factor (HIF) family of transcription factors, especially HIF-1α, mediates the expression of multiple genes to drive the adaptation and progression of tumor cells." (PMID 36494419, 2022). "Hypoxia can regulate cellular senescence, and HIF-1α can promote tumor progression by affecting the expression of specific gene networks under hypoxia." (PMID 36291773, 2022). "Investigation of involved signaling revealed that PMA increased EL4 cell and tumor HIF-1α accumulation and NFκB and JNK activation." (PMID 35250391, 2022). "Recent evidence showed that ncRNAs are involved in the regulation of hypoxia in HCC via HIF-1α and are responsible for the development of an immunosuppressive tumor microenvironment, which facilitates immune evasion of tumor cells." (PMID 36293225, 2022). "Increased HIF-1α results in increased tumor angiogenesis mediated by the up-regulation of pro-angiogenic factors, including vascular endothelial growth factor (VEGF) and platelet-derived growth factor (PDGF)." (PMID 35158918, 2022). "VHL/HIF-1α is a common signaling pathway in KIRC, and mutational inactivation of VHL leads to overexpression of HIF-1α in KIRC, inducing a tumor hypoxic microenvironment that is associated with poorer tumor-specific survival." (PMID 36119517, 2022). "For example, increased lactate levels are instrumental in the promotion of tumor angiogenesis through a hypoxia/HIF-1α-dependent mechanism." (PMID 35246504, 2022). "HIF-1α is a key oncogene that regulates glucose metabolism in tumor cells and is closely related to tumor development, varying in a cell-type-specific manner." (PMID 35434271, 2022). "HIF-1α is a transcription factor widely expressed in humans under hypoxic environments and is highly expressed in most tumor tissues." (PMID 36385964, 2022). "There was a marked increase in the interaction of YAP1 with HIF1α in the tumor samples compared with normal tissues." (PMID 35937460, 2022). "In rapidly growing tumor tissues, HIF-1α is the master regulator of the ability of hypoxic cells to shift their metabolism from oxidative phosphorylation to the less efficient glycolysis to sustain their energy demand, a phenomenon known as the Warburg Effect." (PMID 36230969, 2022). "Due to the regulation of the same set of “core” EMT regulators by METTL4 and lncRNA RP11-390F4.3, the HIF-1α-METTL4-RP11-390F4.3 axis plays a crucial role in hypoxia-induced tumor progression." (PMID 36461076, 2022).
tumor (continued). "We found significant correlations between HIF-1α expression of CTCs and disease-free survival in patients previously treated with fluorouracil analog, especially CTCs in the reflux veins of tumor." (PMID 34998404, 2022). "Our data underscore the notion that GPx2 loss drives tumor heterogeneity, resulting in a metabolically hybrid tumor cell population, which in turn activates both AMPK and HIF1α (GLUT1) signaling, likely due to ROS signaling." (PMID 35193955, 2022). "The most important tumor suppression role of SIRT3 is that it hinders cancer metabolism changes via the inhibition of hypoxia-inducible factor-1a (HIF1α)." (PMID 35927590, 2022). "Studies have shown that HIF-1α acts as an oncogene and participates in tumour growth, metastasis, metabolic rewiring, and chemoresistance." (PMID 35669101, 2022). "This indicates that the upregulation of HIF-1α expression has a promoting effect on tumor growth in vivo." (PMID 35664561, 2022). "The potential effectiveness of the combination of HIF-1α inhibitors with immune-checkpoint-blocking antibodies to augment anti-tumor immunity in irradiated tumors warrants further investigation." (PMID 35805044, 2022). "HIF-1α can trigger anaerobic glycolysis of tumor cells, induce angiogenesis, promote the proliferation, invasion, and migration of tumor cells, and lead to multidrug resistance." (PMID 36003773, 2022). "Hypoxia-inducible factor 1α (HIF-1α) plays a pivotal role in these adaptation mechanisms leading to tumor progression and chemoresistance." (PMID 35681691, 2022). "It is also possible that combination 5-FU and ICB alter tumor immunosuppressive cells through HIF-1α mediated pathways, resulting in decreased MDSCs and Tregs observed in our study." (PMID 35634282, 2022). "One such controlling element is hypoxia inducible factor 1α (HIF-1α) which induces the hypoxic TME and is associated with tumor cell metabolism and exosome release." (PMID 35496046, 2022). "Increased level of HIF1α has been shown to contribute to resistance to sorafenib and lenvatinib in HCC since antiangiogenic drug treatment results in insufficient oxygen supply, and elevated HIF1α and mediate the hypoxic adaptation of tumor cells." (PMID 35692750, 2022). "Second, the expression of CXCLs can also be influenced by hypoxia inducible factor α (HIF-1α) in the tumor microenvironment." (PMID 35181719, 2022). "Because HIF1α regulates tumor angiogenesis, suppressing HIF1α normalizes the vasculature by decreasing the abnormal vasculature generation in tumors." (PMID 34738103, 2022). "In a word, PES1 can promote tumor invasion and lymphangiogenesis by regulating the expression of HIF-1α." (PMID 34976188, 2022). "According to the results, cardamonin can suppress tumor cell growth and proliferation by inhibiting HIF-1α-mediated cell metabolism." (PMID 36289931, 2022). "HIF-1α activates the transcription of numerous genes related to tumor biology, including apoptosis, cell proliferation, angiogenesis, and glucose metabolism." (PMID 36059961, 2022). "Tumor-induced ROS-mediated “pseudo-hypoxia” in CAFs leads to the accumulation of HIF1α and enhanced aerobic glycolysis." (PMID 36203466, 2022). "Hypoxia-inducible factor-1α (HIF-1α) is activated, and the survival of tumor cells is guaranteed to some extent." (PMID 35645817, 2022). "The transcription factor hypoxia inducible factor 1α (HIF-1α) is a key regulator that increases glycolysis and drives tumor development under anoxic conditions." (PMID 34998404, 2022).